CD44 (CD44 molecule (IN blood group))
Diseases named in the same sentence as CD44 in open-access papers (continued):
Sharing a sentence is not in itself a finding about the gene and the disease.
glioma (continued). "Further studies are required to explore the function of CD44 and turn it into a novel site for immune-therapeutic strategy or prognostic biomarker for glioma patients." (PMID 36776876, 2023). "GCL_TI specifically upregulates RG markers TNC, HOPX, PTPRZ1, and VIM, astrocyte markers CLU, LGALS1, as well as genes involved in migration and glioma network formation such as CD44, SPARC, and GAP43 (One peak)." (PMID 36823172, 2023). "PLOD2 modulates the immune microenvironment and tumor progression of glioma, in which CD44 was the critical downstream molecule." (PMID 36776876, 2023). "While CD44 expression is detected across transcriptomic subtypes of gliomas, the highest CD44 expression is present in mesenchymal GBM which portends the worst prognosis." (PMID 36989359, 2023). "Meanwhile, CD44 is also involved in immune suppressor and promote glioma progression in glioma microenvironment." (PMID 36964570, 2023). "In other tumor types, serglycin has been confirmed to promote metastatic tumor growth, and in vitro observations of human glioma tumor cells have shown increased release of the glioma stem cell marker CD44 mediated by serglycin." (PMID 38275375, 2023). "CD44 immunostaining showed the predominance of CD44+ cells among the populations of all four glioma cultures." (PMID 36835465, 2023). "Understanding the CD44 expression pattern and features in glioma better will assist in different optimal strategies for glioma therapies." (PMID 36776876, 2023). "There is a poor prognosis with CD44 overexpression in gliomas, particularly those at WHO stage II and III." (PMID 38066643, 2023). "Further studies were performed, and we found that the enrichment of miR-21 in GA-MSCs exosomes was caused by the miR-21/SP1/DNMT1 positive feedback loop triggered by glioma exosomal CD44." (PMID 37481646, 2023). "Specifically, CD44 was found to critically mediate the activity of glioma cells and macrophages at the scRNA-seq level." (PMID 36776876, 2023). "In agreement with enhanced CD44 and CD133 expression in CEGBCs, their expression in glioblastoma stem cells correlates with cell proliferation, intra-tumor heterogeneity, invasion and poor prognosis in CD44-expressing glioma." (PMID 37147437, 2023). "Several recent studies relevant to the immune function of CD44, a transmembrane glycoprotein as a significant hyaluronic acid receptor, have achieved great success, revealing the critical role of CD44 in immune infiltration in gliomas." (PMID 36776876, 2023). "Hyaluronic acid has been proposed for the targeting of CD44, which is overexpressed on the surface of gliomas and CSCs." (PMID 37376027, 2023). "To date, several CSC surface markers, including CD133, CD24, and CD44, have been reported in glioma." (PMID 37062068, 2023). "We delineated the pattern of CD44 mRNA expression levels regarding disparate WHO-grade gliomas by evaluating data from publicly available databases." (PMID 36776876, 2023). "Immunoblot analysis with antibodies specifically recognizing mesenchymal markers demonstrated elevated CD44 levels in all tested glioma cell cultures, whereas high expression of CHI3L1/YKL40 was found only in WG4 and WG14 cells." (PMID 36900355, 2023). "Then we turned to our most exciting part and evaluated the possible immune-related functions of CD44 in glioma cell growth in the TCGA dataset." (PMID 36776876, 2023). "EHD1 was revealed to promote the cancer stem cell (CSC)-like traits of glioma via interacting with CD44 and suppressing CD44 degradation." (PMID 36776876, 2023). "Taken together, our work demonstrates the significant role of CD44 in the progression and treatment of gliomas." (PMID 36776876, 2023). "is that they examined the Cancer Genome Atlas low‐grade glioma‐GBM and noticed CD44 −positive glioma cells confer TMZ resistance." (PMID 37724133, 2023). "Concerning HA downstream signaling inducing glioma cell migration, receptor CD-44 and RHAMM appear to be involved." (PMID 36980765, 2023).
glioma (continued). "Here, we found that glioma-derived exosomal CD44 upregulated miR-21 expression in MSCs by stimulating the expression of the transcription factor XBP1s." (PMID 37481646, 2023). "In the glioma model in vivo, CD44 promoted cancer stem cell phenotype and radiation resistance, while CD44 expression correlated with hypoxia-induced gene signatures and poor survival in glioblastoma patients." (PMID 38067149, 2023). "By combining CDCP1, CD44 and ITGAM, a prognostic risk model was established and validated to predict 1-year, 3-year, and 5-year survival in glioma patients." (PMID 35410293, 2022). "CD44 expression plays significant role in invasion and metastasis of glioma cells and higher levels of CD44 in patients act as a glioblastoma cancer stem cell marker." (PMID 36185622, 2022). "Although the mechanism of action is not fully understood, galangin has been shown to inhibit endothelial cell migration and angiogenesis by downregulating CD44, a multifunctional cell surface glycoprotein which is over expressed in glioma (brain cancer)." (PMID 35479311, 2022). "We have demonstrated that glioma stem-like cells expressing CD44 to a high level at the tumor invasion zone in the periphery of GBM." (PMID 35624954, 2022). "SPP1/CD44 signaling of the glioma-infiltrated macrophages was shown to interact with the glioma cells and induce mesenchymal glioma formation." (PMID 35884391, 2022). "In order to obtain insight into which kind of microglial secreted factors depend on CD44 in the context of glioma, we used a co-culture model in which primary microglia were incubated together with GL261 cells for 24h." (PMID 35992852, 2022). "Authors showed that by blocking CD44 on macrophages, the latter acquire an M1 phenotype resulting in reduced glioma proliferation and migration and increased survival of tumor-bearing mice." (PMID 35992852, 2022). "we performed the co-expression analysis and confirmed that CAPG2 positively correlates with the expressions of well-defined glioma stem cell marker genes, including Sox2, CD44, MYC and CCND1." (PMID 35898895, 2022). "Initiation of tau pathology in the brain by sCD44 and overexpression of CD44 in glioma represents the pathological relation between GBM and neurodegeneration." (PMID 36422293, 2022). "In our previous research, we demonstrated that CD44, as an important HA receptor, binds to HA, which is crucial for glioma progression." (PMID 35410993, 2022). "A direct comparison of the levels between WT and CD44-/- microglia in the presence of glioma cells revealed significantly lower levels in CD44-/- microglia." (PMID 35992852, 2022). "To study the impact of CD44-positive myeloid cells on glioma growth and progression in vivo, we carried out intracranial orthotopic injections in CD44fl/fl (floxed) and Csf1r-Cre/CD44fl/fl conditional knockout (cKO) mice." (PMID 35992852, 2022). "Particularly, among the proteins over-expressed in GBM-sEVs, we noted the glioma-associated extracellular matrix antigen Tenascin C (TNC), the stemness-associated CD109 antigen, the tumor-associated CD44 antigen, the Ras suppressor protein 1 (RSU1)." (PMID 36009432, 2022). "While CCL2 levels were similar for glioma cells co-culture with WT or CD44-/- microglia, IL-6 mRNA levels were reduced by half in glioma cells co-cultured with CD44-/- microglia, compared to WT." (PMID 35992852, 2022). "In summary, EGCG limits the invasiveness of glioma cells by blocking the cleavage of CD44 and disturbing the restructuring of the actin cytoskeleton through inhibition of MT1-MMP." (PMID 35328780, 2022). "Tissue invasion and metastasis, which includes glioma invasiveness signaling with the up-regulation of CD44 and matrix metalloproteinase 9 (MMP9), was activated after 6 h of treatment with TPA." (PMID 35328637, 2022).
glioma (continued). "We found that glioma stem-like cells with a high expression of CD44 exist in the tumor invasion zone of the tumor periphery in highly invasive GBM." (PMID 35624954, 2022). "It has been demonstrated that high levels of CD44 are necessary to generate infiltrative glioma mouse models and that treatment with anti-CD44 antibodies inhibited tumor progression, possibly due to altered hyaluronic acid binding." (PMID 36276147, 2022). "Three mouse glioma lines were tested and presented disrupted invasiveness in brain slices from CD44-/- mice." (PMID 35992852, 2022). "In line with the vast body of evidence implicating CD44 in glioma progression, we observed a significant reduction in the proliferative capacity of the well-established GBM in vitro model U251MG, upon depletion of CD44 by CRISPR/Cas9 gene editing." (PMID 35954411, 2022). "We show that CD44, expressed by cells of the tumor microenvironment, plays a major role in glioma invasion." (PMID 35992852, 2022). "CD44, a marker of human GSCs, increased, indicating changes in mRNA expression in human glioma stem cells after several hours of exposure to sevoflurane." (PMID 36363571, 2022). "Based on CIBERSORT analysis, Du and colleagues have proposed that CD44+ glioma cells communicate with pro-inflammatory microglia-derived brain macrophages through SPP1-CD44 signalling." (PMID 36555253, 2022). "Gliomas of TrMRS high-risk group presented with significantly higher expression level of CD274 (PD-L1), CD276 (B7H3), HAVCR2 (TIM3), PD1 (CD279, PDCD1), and CD44." (PMID 36386216, 2022). "In agreement with this, a recent study has found that HA synthetized by glioma cells binds CD44 on myeloid cells thereby triggering their immunosuppressive polarization." (PMID 35992852, 2022). "In contrast to TMZ treatment, the expression of stem cell markers, CD133 and CD44, remained unchanged under BEV treatment; thus, glioma cell profiles associated with stemness would remain stable." (PMID 35448036, 2022). "Meanwhile, CD44 predominantly expresses in GBM mesenchymal subtype, and gene ontology (GO) and Kyoto Encyclopedia of Genes and Genomes (KEGG) analyses reveal that CD44 positively coexpressed genes are closely related to glioma immunity." (PMID 35187044, 2021). "OPN also shares a perivascular expression pattern with CD44 in glioma CSCs and activates its signalling, increasing glioma aggressiveness, growth, stemness and radiation resistance." (PMID 34944493, 2021). "We discovered the immune characteristic of CD44 in glioma, which plays a critical role in clinical outcomes." (PMID 35187044, 2021). "A deeper understanding of the role of CD44 in glioma will guide promising research in novel glioma therapeutic strategy." (PMID 35187044, 2021). "HAS3 silencing or treatment with the CD44 antibody increased the number of autophagic vesicles in glioma cells." (PMID 33986244, 2021). "Activated NF-κB can mediate the activation of STAT3, CEBPB, and TAZ by upregulating the expression of CD44, vimentin, and N-cadherin, thereby promoting the invasion, angiogenesis, and therapeutic resistance of glioma." (PMID 34246306, 2021). "The results confirmed the relative expression levels of HA, HAS3, and CD44 in glioma were higher than those in HUVEC cells." (PMID 33986244, 2021). "Reduction of CD44 surface marker expression, involved in tumor proliferation and migration, was reported after bromelain treatment on leukemia, melanoma and glioma cells." (PMID 33986357, 2021). "Taken together, this study provided a single-cell atlas of one high-grade glioma and revealed a critical role of macrophage-mediated SPP1/CD44 signaling in glioma progression, indicating that the SPP1/CD44 axis is a potential target for glioma treatment." (PMID 34805184, 2021).
glioma (continued). "CD44 was closely related to the invasion and migration of glioma cells due to its key role in the adhesion between glioma cells." (PMID 34689169, 2021). "Both osteopontin and CD44 correlate with a poor overall survival in patients, suggesting a role of perivascular-niche astrocytes in supporting glioma stem cells." (PMID 34690699, 2021). "Altogether, this study revealed a critical role of macrophage-mediated SPP1/CD44 signaling in high-grade glioma, providing a new therapeutic target for the precision treatment of glioma." (PMID 34805184, 2021). "Whereas, tumor is constituted by malignant cells and surrounding stromal cells, we know few about the heterogeneity of CD44 transcription in glioma at single-cell resolution until now." (PMID 35187044, 2021). "They demonstrate these novel micelles functionalized with Tween 80 to move across the BBB, and both target and treat gliomas by combined effects of CD44-mediated endocytosis and glutathione-mediated intracellular release of curcumin." (PMID 33118056, 2021). "Our work also found that CD44 can be a prognostic biomarker, whose transcription level is related to malignancy glioma and poor prognosis in two notable glioma cohorts." (PMID 35187044, 2021). "CD44 is related to immunity in glioma, CD44+ malignant tumor cells are in MES-1-like state, and CD44+ TAMs are in M2 phenotype." (PMID 35187044, 2021). "To clarify the role of CD44 in glioma, we explored its function at bulk-transcriptome, spatial and single-cell transcriptome levels." (PMID 35187044, 2021). "Next, we explored the expression of the immunomodulators with direct interaction to CD44 among the glioma CD44+ cells." (PMID 35187044, 2021). "As expected, HSA3 silencing or the CD44 antibody treatment increased the number and intensity of yellow fluorescent dots in glioma cells compared with cells in the control group." (PMID 33986244, 2021). "To uncover the correlation between immunotherapy and CD44 in glioma, we extracted bulk RNA-seq data of patients with recurrent GBM receiving adjuvant, postsurgical PD-1 blockade therapy from this study." (PMID 35187044, 2021). "Alterations in HA metabolism induced by silencing HAS3, blocking its binding with the receptor CD44, or administering 4-MU inhibited autophagy flux, arrested the cell cycle at G1 phase, and subsequently inhibited glioma cell proliferation in the present study." (PMID 33986244, 2021). "HAS3 silencing or treatment with the CD44 antibody combined with CQ exerted a synergistic effect on reducing the viability of glioma cells and levels of the Ki67 protein." (PMID 33986244, 2021). "Compared with the lower expression of CD44 group in whole-grade glioma, patients with higher CD44 expression have significantly shorter survival." (PMID 35187044, 2021). "The results indicate that CD44 is positively associated with the immune score and stromal score in TCGA and CGGA glioma databases, which suggests that CD44 does work in glioma immunity." (PMID 35187044, 2021). "We found that the expression levels of FANCD2 and CD44 genes were related to the survival of Chinese glioma patients according to the data from the mRNAseq_325 dataset in the CGGA database." (PMID 34689169, 2021). "Although these approaches affect all CSPGs on cancer cells, our data suggest that CS chains can directly or indirectly modulate CD44 stability on the surface of glioma cells." (PMID 34944101, 2021). "identify another mechanosensation mediator in the CD44-HA interaction that also enhances glioma cell invasion." (PMID 35127517, 2021). "The inhibition of HAS3 or CD44 in vivo significantly decreased the glioma volumes, extended the survival time of mice, and downregulated Ki67 expression compared with controls." (PMID 33986244, 2021). "CD44-specific antisense oligonucleotide, which prevents CD44 expression, substantially inhibits invasion of glioma cells." (PMID 34149360, 2021).
glioma (continued). "First, the relative expression of HA, HAS3, and CD44 were determined in five glioma cell lines (LN229, U251, U87, T98, A172) and HUVEC cells." (PMID 33986244, 2021). "HAVCR2 plays almost the same immunosuppressive functions as PD-1 in glioma, and we also found that CD44 shows a consistent correlation with HAVCR2 and PD-1 in glioma." (PMID 35187044, 2021). "The SKN and DTX-loaded microemulsion was bifunctionalized with A1411 aptamer and HA that exhibited targeted delivery via specifically binding with CD44/nucleolin-overexpressed glioma." (PMID 35431911, 2021). "Nevertheless, our confocal microscopy images confirmed that CD44 and integrin β1 are largely co-localized on the invasive fronts of control glioma cells." (PMID 34944101, 2021). "Herein, we integrated bulk RNA-sequencing data (RNA-seq) and single-cell RNA-seq data to investigate the immunosuppressive role of CD44 in glioma." (PMID 35187044, 2021). "Epidermal growth factor stimulation promotes CD44 mRNA expression, which results in glioma cell invasion." (PMID 34149360, 2021). "We also checked the spatial preference of CD44 in glioma and found that CD44 distributes in the perinecrotic zone within tumor." (PMID 35187044, 2021). "The expression levels of Wnt-related genes, including β-catenin, GSK-3β, cyclin D1, and CD44 were all decreased in AEG-1 knockdown glioma cells compared to that in the control cells." (PMID 34462446, 2021). "TAMs are the major immune cells in GBM, which is in accord with our finding that CD44 acts in glioma immunity." (PMID 35187044, 2021). "We interrogated tumours of differing grade and observed a higher expression of CD133 and CD44 in glioblastoma compared to lower grade gliomas in TCGA-LGG-GBM dataset." (PMID 34066147, 2021). "First of all, the specific molecular mechanisms of the effects of FANCD2 and CD44 on the proliferation, migration and invasion of glioma cells need to be elucidated." (PMID 34689169, 2021). "These were immunohistochemically double stained with antibodies against the proliferation-associated antigen Ki67 and marker proteins for glioma stem cells (CD133, Nestin, Musashi, CD15, CD44), and differentiated glioma cells (GFAP, MAP2c)." (PMID 34170383, 2021). "Silencing HAS3 expression or blocking CD44 inhibited glioma cell proliferation in vitro and in vivo." (PMID 33986244, 2021). "CD44 promoted the resistance of glioma cells to radiotherapy and chemotherapy, and promoted tumor cell formation and other biological functions." (PMID 34689169, 2021). "Conversely, the disruption of the CD44/EGFR complex reduces ERK1/2 activation in U87MG glioma cells." (PMID 33744285, 2021). "CD44 is a well-known marker of glioma cancer stem cells (CSCs) and plays important roles in tumor initiation and progression." (PMID 35187044, 2021). "Given the obvious heterogeneity in glioma, we further investigated the prognostic value of CD44 among different WHO grades, IDH types, 1p19q states, and recurrent status." (PMID 35187044, 2021). "In both the TCGA glioma and CGGA glioma, samples with strong CD44 transcription are primarily having wild-type IDH, but the ones with low CD44 expression have IDH mutation, which can also be discovered among GBM groups." (PMID 35187044, 2021). "Next, we established stable U251 cell lines with knockdown of HAS3 and CD44 to further analyze the effects of HAS3 and CD44 on glioma cell viability and proliferation in vivo." (PMID 33986244, 2021). "To further verify the pro-survival effect of HAS3 and CD44, we over-expressed HAS3 and CD44 in glioma cell lines." (PMID 33986244, 2021). "CD44 expression level was elevated after irradiation or temozolomide treatment in mouse glioma model, which indicated CD44 is involved in resistance to chemoradiation in glioma." (PMID 35187044, 2021).